METTL1 (methyltransferase 1, tRNA methylguanosine)
Diseases named in the same sentence as METTL1 in open-access papers (continued):
Sharing a sentence is not in itself a finding about the gene and the disease.
cancer (109 papers, 2014 to 2026). A tumor composed of atypical neoplastic, often pleomorphic cells that invade other tissues. "METTL1-mediated m7G modification affects codon translation and is also associated with various other cancers, such as lung cancer, leukemia, nasopharyngeal carcinoma, neuroblastoma, and gastric cancer." (PMID 41501031, 2026). "METTL1 is a key tRNA methyltransferase located in the region of chromosome 12 (12q13-14), which is frequently amplified in various cancers and closely associated with tumorigenesis." (PMID 41501031, 2026). "The review aims to summarize the diverse roles of METTL1 in various cancers, focusing on the mechanisms underlying tumorigenesis, progression, and metastasis." (PMID 40809384, 2025). "In some cancer cells, METTL1 stabilizes mRNAs encoding pro-proliferative or anti-apoptotic genes, promoting tumor cell survival and growth." (PMID 41562049, 2025). "The associations among METTL1, m7G modification, and the metastatic potential of tumors underscore the importance of this enzyme in the broader context of cancer biology." (PMID 40809384, 2025). "The diverse functions of METTL1 highlight its importance in maintaining normal cellular processes and underscore its potential as a valuable therapeutic target for cancers associated with disrupted RNA methylation." (PMID 40809384, 2025). "Emerging evidence indicates that METTL1 is aberrantly expressed in various cancers, where its upregulation is associated with enhanced tumor cell proliferation, migration, chemoresistance, and poor prognosis." (PMID 41562049, 2025). "The m7G methyltransferase METTL1 has been implicated in the occurrence and progression of several cancers." (PMID 40443650, 2025). "Extensive studies have demonstrated that METTL1 is aberrantly expressed in multiple cancer types, with high expression closely associated with poor prognosis, highlighting its central role in cancer biology." (PMID 41562049, 2025). "Overall, the available evidence confirms that METTL1 is associated with immune checkpoints, making it an important regulator of cancer immunology and a therapeutic target." (PMID 40809384, 2025). "This coupling with metabolic pathways partially explains why METTL1 is frequently upregulated in various cancers and is closely associated with tumor metabolic reprogramming." (PMID 41562049, 2025). "In line with our findings, recent evidence has associated increased METTL1 expression with the occurrence of several cancer types." (PMID 37516825, 2023). "Increased expression of METTL1 has been associated with various types of cancer, and chemotherapy sensitivity." (PMID 37660182, 2023). "Conversely, increased mRNA translation efficiency due to METTL1 upregulation is inextricably linked to cancer development." (PMID 37710294, 2023). "At the pathological level, increased METTL1 expression is associated with tumour aggressiveness in several cancer types." (PMID 37516825, 2023). "Conditional Mettl1 loss led to increased expression of autophagy and genotoxic stress markers in cancer cells." (PMID 37660182, 2023). "In this study, we aim to gain more insights into the underlying mechanism of METTL1 and immune-related factors in pan-cancer research." (PMID 35432338, 2022). "METTL1 expression was positively correlated with PVRL2 in nearly all cancers, whereas, it was negatively associated with KDR and CD274 in nearly all cancers." (PMID 35432338, 2022). "The NSUN2 and METTL1 tRNA modification genes have been associated with resistance to anti-cancer therapy." (PMID 35721477, 2022). "METTL1 has been reported to be highly expressed in a variety of cancers and was associated with tumor initiation, metastasis and chemo-sensitivity." (PMID 36226166, 2022). "In summary, loss-of-function screens of cancer cell lines support the biological importance of several METTLs, notably METTL1, METTL3, METTL14, METTL16 and METTL17, in promoting cancer cell growth and survival." (PMID 34285249, 2021).
cancer (continued). "Previous research has shown that the abnormal level of METTL1 is strongly associated with the tumourigenesis and progression of cancer." (PMID 34936728, 2021). "Then, we focused on a top candidate, METTL1, and investigated functional annotation and pathway enrichment of METTL1-associated proteins in human cancer." (PMID 34285249, 2021). "Recent studies have revealed that the dysregulation of tRNA m7G methyltransferase METTL1 is associated with a malignant phenotype in a number of disorders, including cancer." (PMID 34936728, 2021). "Collectively, these observations indicate that METTL1 may influence immunotherapy responses in certain cancers, but its pan-cancer relevance and underlying mechanisms require further investigation to inform individualized immunotherapy strategies." (PMID 41562049, 2025). "In addition, the upregulated expression of METTL1/WDR4 complex in a variety of cancers is associated with malignancy and poor survival." (PMID 39850560, 2024). "Furthermore, METTL1 inhibition renders cancer cells more susceptible to the effects of chemotherapeutic agents, offering potential in combination therapy for enhanced effectiveness." (PMID 37660182, 2023). "METTL1 loss in these cancer cells resulted in elevated migration potential in vitro." (PMID 37612540, 2023). "Notably, aberrant expression of the m7G -modified methyltransferase METTL1 was associated with a range of cancers." (PMID 36071474, 2022). "For example, METTL1 was highly expressed in most tumor tissues, and a univariate Cox analysis showed that the high expression of METTL1 was significantly associated with poor survival in cancer patients." (PMID 36226166, 2022). "While high METTL1 levels might be implicated in the cancer cell homeostasis by stabilizing tRNA, its inactivation decreases the pseudourydilation and the 7-guanyl-methylation, which in turn destabilize the tRNAs." (PMID 33430133, 2021). "Increased angiogenesis is often associated with enhanced cancer cell proliferation and tumor growth, which might explain why METTL1-KD teratomas exhibited increased cell proliferation and enhanced growth." (PMID 32698871, 2020). "To examine the effects of double knockdown of NSUN2 and METTL1 on further chemotherapeutic agents other than 5-FU, we used cisplatin, a platinum-containing anti-cancer drug that binds to and causes crosslinking of DNA, and paclitaxel, a microtubule-stabilizing mitotic inhibitor." (PMID 25233213, 2014). "In summary, our findings suggest that inhibiting METTL1 alone or in combination with chemotherapeutic agents could enhance the elimination of cancer cells within a tumour by rendering them more susceptible to genotoxic stress and increasing their responsiveness to chemotherapy." (PMID 37660182, 2023). "In addition, recent studies also uncovered that METTL1 is upregulated in cancers and associated with chemosensitivity, however, the detailed functions and molecular mechanisms of tRNA m7G modification in ESCC are still largely unknown." (PMID 35304469, 2022). "In summary, transcriptomic and proteomic profiles of METTLs across a broad range of cancer types and their associations with clinical outcomes indicated that a subset of METTLs, such as METTL1, METTL7B, and NTMT1, might act as oncogenes, while METTL7A acts as a tumor suppressor." (PMID 34285249, 2021). "METTL1 modifies the m7G site of tRNA to affect the translation efficiency of specific codons, thereby regulating the occurrence and development of cancer." (PMID 41501031, 2026). "In various cancers, METTL1 affects tumor occurrence and progression by regulating tRNA codon-specific translation." (PMID 41501031, 2026). "For example, analyzing how m6A modification mediated by METTL3 in local neuronal synapses regulates synaptic plasticity, or the “cross-talk” between immune cells and cancer cells in the tumor microenvironment by METTL1." (PMID 41194259, 2025).
cancer (continued). "Specifically, dysregulated m7G‐related enzymes, such as METTL1 and WDR4, are implicated in multiple cancer types." (PMID 40842081, 2025). "METTL1, a methyltransferase involved in the m7G modification of RNA, is differentially expressed across various cancer types." (PMID 40809384, 2025). "Role of METTL1 in mRNA methylation and cancer pathogenesis: METTL1-mediated mRNA methylation also plays a key role in tumorigenesis." (PMID 40809384, 2025). "Previous studies have demonstrated the ability of METTL1 to promote cancer cell migration and invasion." (PMID 39870616, 2025). "The article integrates recent research findings to highlight significant discoveries regarding METTL1, emphasizing its potential as a therapeutic target in cancer treatment." (PMID 40809384, 2025). "The enzymatic activity of METTL1, a methyltransferase, is key to its role in diseases such as cancer." (PMID 40360483, 2025). "In recent years, increasing evidence has highlighted the critical role of the m7Gmethyltransferase METTL1 in various cancers, particularly in modulating the tumor immune microenvironment, influencing immune evasion, and regulating sensitivity to immunotherapy." (PMID 41562049, 2025). "Collectively, METTL1 functions as a pivotal driver of cancer progression and represents a promising biomarker and therapeutic target, highlighting the potential of targeting tRNA m7G modification in precision oncology." (PMID 41562049, 2025). "In summary, METTL1, as a tRNA m7G methyltransferase, plays a multi-layered and critical role in cancer development and tumor immune regulation." (PMID 41562049, 2025). "In various cancer types, METTL1 enhanced the proliferation and invasion of tumor cells by activating the translation of mRNAs containing codons decoded by m7G-modified tRNAs." (PMID 40809384, 2025). "It was found that METTL1 can regulate m7G tRNA modifications and expression across multiple cancer types." (PMID 41208200, 2025). "METTL1 orchestrates tumor immune evasion across multiple cancers by modulating immunosuppressive microenvironments through distinct mechanisms, positioning it as a promising therapeutic target to enhance immunotherapy efficacy." (PMID 40809384, 2025). "Evidence indicates that overexpression of METTL1 promotes the proliferation, migration, and invasion of cancer cells, suggesting that it contributes to cancer development." (PMID 40809384, 2025). "Recent studies have suggested that mRNA internal m7G and its writer protein METTL1 (methyltransferase 1, tRNA methylguanosine) are closely related to cell metabolism and cancer regulation." (PMID 40870000, 2025). "Its multifaceted roles establish METTL1 as a critical target in cancer research, offering promising avenues for therapeutic intervention." (PMID 40809384, 2025). "This modification was previously reported in yeast, but recent studies have shown that METTL1/WDR4-mediated m7G tRNA modification is strongly linked with tumorigenesis and cancer progression in mammals." (PMID 40360483, 2025). "Loss of METTL1 reduces mature let-7e levels by 60%, upregulating the oncogenic target High Mobility Group AT-Hook 2 (HMGA2) and promoting cancer cell migration." (PMID 40809384, 2025). "METTL1, named as methyltransferase-like 1, is located on a region of chromosome 12 (12 q13-14) that is frequently amplified in cancers." (PMID 40770782, 2025). "METTL1 plays a significant role in the progression of various cancers by regulating key signaling pathways, mRNA translation, and immune modulation." (PMID 41256854, 2025). "Many studies have shown that METTL1 facilitates cell proliferation in cancer by regulating several different targets or pathways." (PMID 39979979, 2025). "In a study investigating the development of an OC prognosis model, METTL1 showed significant correlations with overall survival, cancer status, and immune cell profiles." (PMID 41430564, 2025).
cancer (continued). "Overall, METTL1 acts as a central regulator of cancer biology by integrating RNA modification-mediated translational control and mRNA stability, thereby driving tumor growth, metastasis, and therapy resistance." (PMID 41562049, 2025). "Functionally, the overexpression of METTL1 increases cancer cell proliferative capacity and accelerates cell cycle advancement, whereas silencing of METTL1 suppresses these cellular processes." (PMID 40986143, 2025). "The aim of this review is to dissect the multifaceted roles of METTL1 in cancer biology, focusing on its mechanisms of action and therapeutic potential." (PMID 40809384, 2025). "Multiple in vivo cancer models reveal that METTL1 plays a central immunoregulatory role by controlling PMN-MDSC accumulation in the tumor microenvironment, thereby promoting ICC progression." (PMID 41562049, 2025). "The findings presented here highlight potential therapeutic targets related to METTL1 for cancer treatment." (PMID 40809384, 2025). "In recent years, there has been renewed interest in studying the role of METTL1 in cancer growth and progression." (PMID 40809384, 2025). "As the role of METTL1 in cancer initiation and progression becomes increasingly evident, its potential as a therapeutic target has attracted growing attention." (PMID 41562049, 2025). "In cancer cells, METTL1-dependent m7G modifications are often enriched on oncogenes or signaling pathway-related mRNAs, supporting their efficient expression and facilitating proliferation, migration, and drug resistance." (PMID 41562049, 2025). "The expression of METTL1 in cancer is regulated by multiple upstream factors and epigenetic mechanisms." (PMID 41562049, 2025). "Methyltransferase-like 1 (METTL1) is a methyltransferase that modulates the RNA methylation process and has been increasingly investigated in cancer research over the past decade." (PMID 40809384, 2025). "In summary, these observations reveal that METTL1 is essential for the proliferation of cancer cells." (PMID 39979979, 2025). "In HCC, WDR4 interacts with METTL1 to synergistically regulate m7G mRNA modification, thereby promoting cancer progression." (PMID 41256854, 2025). "In a variety of cancers, m7G modification promotes cancer cell growth, proliferation and tumor formation through the METTL1/WDR4/Arg-TCT-4-1 axis." (PMID 38654314, 2024). "Another study demonstrated that the reduction of METTL1/WDR4 hinders the translational efficacy of the oncogene lysyl oxidase-like 2 (LOXL2), which is a cancer-causing enzyme that promotes the cross-linking of elastin and collagen in the extracellular matrix." (PMID 39019857, 2024). "Utilizing expression profiles of 33 pan-cancer datasets from The Cancer Genome Atlas (TCGA) project, we observed aberrant expression of METTL1 and WDR4, known as m7G methyltransferase, across multiple cancer types." (PMID 38384713, 2024). "FOXM1 promoted the proliferation, invasion and colony formation of LUAD cells, therefore FOXM1 mediated the cancer‐promoting effect of METTL1 in LUAD." (PMID 38967523, 2024). "Another important challenge to overcome when facing cancer is tumor metastasis, and METTL1 appears to play a role in this critical scenario." (PMID 38476632, 2024). "Higher expression of METTL1 and its cofactor WDR4 were significantly associated with poorer overall survival in LGG and LIHC, indicating an oncogenic role of the METTL1/WDR4 methyltransferase in these cancers." (PMID 39041608, 2024). "The classical m7G writer METTL1 was reported to regulate the accumulation of PMN-MDSCs in various cancers." (PMID 38385078, 2024). "In summary, METTL1 emerges as a versatile contributor to cancer biology by intricately regulating protein translation." (PMID 38476632, 2024). "A pan-cancer examination has shown that METTL1, an enzyme responsible for m7G methylation, is positively correlated with Treg cell numbers in diverse cancer subtypes." (PMID 39372415, 2024).
cancer (continued). "The METTL1/WDR4 complex is capable of facilitating tRNA m7G modifications in several types of cancer cells." (PMID 39019857, 2024). "We observed a generally low frequency of amplification and deletion in m7G writer genes across 33 cancer types (<10%), apart from METTL1, which showed amplification across various cancer types, particularly in SARC and GBM (~15%)." (PMID 39041608, 2024). "The deletion of METTL1 reduces cancer cell proliferation and promotes cell apoptosis, thus inhibiting cancer metastasis." (PMID 39456272, 2024). "The accurate detection of internal m7G modifications is of paramount significance, given recent associations between altered m7G deposition and elevated expression of the methyltransferase METTL1 in various human cancers." (PMID 38566310, 2024). "Studies have suggested a crucial function of m7G methyltransferase-related genes in the incidence and growth of cancer, especially the m7G regulatory factors METTL1 and WDR4." (PMID 39440068, 2024). "Recent studies have suggested that mRNA internal m7G and its writer protein METTL1 are closely related to cell metabolism and cancer regulation." (PMID 39198433, 2024). "In particular, we noted that cancer-related genes including METTL1, ALKBH2, PSPH, PTPRC, and TRIP13 contributed the most to the identification, which indicated the great biological interpretability of our model." (PMID 38243719, 2024). "Overall, our result indicates a synergistic expression of METTL1/WDR4 genes in cancers, consistent with their functions as a complex." (PMID 39041608, 2024). "Increasing evidences show that m7G disposition on tRNA by METTL1 are involved in important cellular functions and its dysregulation can lead to different diseases, specially cancer." (PMID 38566310, 2024). "Three ICB therapeutic biomarkers (MSI, TMB, and CD274) showed significant correlation with METTL1 in a few cancers." (PMID 39289775, 2024). "When examining the role of METTL1 in various cancer types, the common theme emerges as a regulator of proliferation and tumorigenesis." (PMID 38476632, 2024). "This highlights METTL1’s potential as a therapeutic target and positions it as a key player in comprehending the dynamics of cancer progression." (PMID 38476632, 2024). "As for protein level, HCC and para-carcinoma tissues were used for western blotting and IHC analysis, the results confirmed that METTL1 was upregulated in HCC." (PMID 39616161, 2024). "Here, we show that N7-guanosine methylation (m7G) of tRNAs, mediated by METTL1, regulates survival to stress conditions in cancer cells." (PMID 37660182, 2023). "To investigate the potential significance of METTL1-mediated methylation in cancer cells, we examined METTL1 expression in this population." (PMID 37660182, 2023). "METTL1 is highly expressed in various types of cancer, highlighting its significant role in tumorigenesis." (PMID 37660182, 2023). "Our study uncovers the role of m7G methylation of tRNAs in stress responses and highlights the potential of targeting METTL1 to sensitise cancer cells to chemotherapy." (PMID 37660182, 2023). "Co-overexpression of NSUN2 and METTL1 can enhance the cancer cell resistance to 5-FU by stabilizing tRNA and preventing rapid tRNA degradation (RTD) pathways." (PMID 36923941, 2023). "At the same time, the researchers found that the m7G tRNA methyltransferase METTL1 (methyltransferase like 1) is related to the growth of cancer cells." (PMID 37081394, 2023). "It will be interesting in future studies to explore the immune landscape in the context of METTL1 to gain a more comprehensive understanding of the implications for tumour immune evasion in PCa other cancer types." (PMID 37516825, 2023). "Taken together, these data demonstrated that m7G tRNA modification can impact the carcinogenesis and development of cancer in a variety of ways, METTL1 can be used as a marker for diagnosis and prognosis and therapeutic target in cancer." (PMID 36923941, 2023).